CD44 (CD44 molecule (IN blood group))
Diseases named in the same sentence as CD44 in open-access papers (continued):
Sharing a sentence is not in itself a finding about the gene and the disease.
cancer (continued). "Aldehyde dehydrogenase 1 (ALDH1) and CD44 have been established as biomarkers for predicting the survival of many types of cancer patients." (PMID 30372483, 2018). "In cancer cells, it has been reported that the splicing pattern of CD44 is altered as EMT progresses, marked by a shift in expression from CD44v to CD44s, the standard form of CD4427." (PMID 29396430, 2018). "Altogether these aspects impact negatively on our understanding of the biological and clinical relevance of CD44 isoforms in cancer and other diseases, urging nomenclature standardization." (PMID 29983670, 2018). "CD44 expression is also upregulated in subpopulations of cancer cells and is recognized as a molecular marker for cancer stem cells (CSC)." (PMID 29747682, 2018). "Of note, most of these approaches focus on interactions occurring between molecules in solutions, and there is limited information regarding the interactions between immobilized HA and CD44 and/or cancer cells." (PMID 30375477, 2018). "The physiological importance of the interactions between hyaluronic acid (HA) and its main membrane receptor, CD44, in pathological processes, e.g. cancer, is well recognized." (PMID 30375477, 2018). "Different isoforms of CD44 are produced by alternate splicing of the pre-mRNA and have been found in different cancer cells." (PMID 29500465, 2018). "It has also been shown that CD44 forms complexes with CD147 at the cell surface of cancer cell lines, which is indicative of the pivotal and complex role CD147 plays in KRas-driven tumors." (PMID 29899869, 2018). "BCCs from cell lines and blood from BC patients were analysed for these three membrane proteins by flow cytometry, along with known markers of cancer stem cells (CSCs), CD44, CD24 and Oct4, aldehyde dehydrogenase 1 (ALDH1) activity and telomere length." (PMID 29321622, 2018). "On the other hand, several recent studies suggest a link between CD44 expression and cancer stem cell properties and EMT." (PMID 29652830, 2018). "While levels of F77-glycosylated CD44 were higher in the majority of men with cancer compared to the value of serum from healthy controls, our study only involved a small number of clinical samples." (PMID 29423071, 2018). "It is of interest that the Rho inhibitor markedly enhanced CD44 expression at the level of some CD44−/low cells that differentiate into CD44high cells and acquire cancer stem cell properties." (PMID 29652830, 2018). "Subsequent ablation of CD44 led to inhibition of glycolysis, increase in ROS and enhancement of chemotherapeutic drug effect in these cancer cells." (PMID 29922594, 2018). "Spheroid formation ability of cancer stem like CD44+/CD26+ cells was significantly inhibited by carbon ion beam combined with CDDP." (PMID 29599911, 2018). "A pharmalogical inhibitor of NF-κB also reduced CD44 expression and consequently, cancer cell proliferation and invasiveness were decreased." (PMID 29747682, 2018). "These ternary complexes processed an efficient targeting cancer cell transfection due to the CD44‐targeting ability, and B‐PEI induced endosome escape and the strong nucleotide‐binding affinity of catechin." (PMID 29721408, 2018). "The roles that CD44 isoforms expression plays in the pathogenesis of cancer are under investigation." (PMID 29747682, 2018). "Recently, researchers have started to investigate HA as a targeting moiety for NP PS enhanced drug delivery in PDT, since it can specifically bind to various cancer cells that over-express CD44 which is a HA tumour receptor." (PMID 30322132, 2018). "A CD44/Zeb1 loop then initiates two-step transition of precancerous cells to cancer cells via a stable intermediate population of cancer-generating cells." (PMID 29930325, 2018). "CD44 is proposed to be involved in increasing the motility of cancer cells and differentiation of cancer stem cells." (PMID 29510526, 2018).
cancer (continued). "Future studies wouldneed sophisticated experimental models to understand spatiotemporal expression andfunction of CD44 isoforms during cancer progression." (PMID 31069317, 2018). "Many cancer cells are known to overexpresses HA-biding receptors, such as CD44, LYVE-1 receptors, and RHAMM." (PMID 30961058, 2018). "CD44 mediates its effects on the cancer cell by activating signaling pathways including protein kinases, by activating transcription factors and by modulating the cytoskeletal architecture." (PMID 29747682, 2018). "We utilized a K-Ras-initiated model of lung AC12 to search for a CD44/Zeb1 loop in vivo, and address its potential role in cancer cell generation." (PMID 29930325, 2018). "This is consistent that cancer stem cell marker CD44 is abolished upon the combination treatments since telomerase drives stemness in cancer and stem cells." (PMID 30250641, 2018). "Being both a receptor for extracellular matrix components and a co-factor for growth factors and cytokines, CD44 is a well-established cancer stem cell marker with great prognostic and therapeutic potentials." (PMID 29855333, 2018). "Cancer stem cells are indicated by cell surface markers CD44+/CD24low and CD44+/CD49f+/CD133/2+ as well as ALDH1 activity." (PMID 29881724, 2018). "In contrast to targeting HA synthesis, CD44 as the primary HA receptor is another target for cancer therapy." (PMID 30135409, 2018). "Overexpression of CD44 can be observed in cancer cells including breast, pancreas, gastric, prostate, ovarian and colon, making CD44+ a biomarker of cancer cells." (PMID 30283149, 2018). "CD44 is an adhesion molecule expressed at the cell surface and is thought to be a marker of cancer stem cells." (PMID 29434323, 2018). "Transient knock-down of Smoothened (Smo), a critical component of the hedgehog signaling pathway, inhibited the expression of MMP2 and MMP9 in CD44-positive cancer cells." (PMID 29747682, 2018). "Since PKM2 expression is negatively regulated by CD44, which is a marker for cancer stem cells and a repressor of ROS production, we next examined the expression regulation of PKM2 by CD44 knockdown treatment." (PMID 30257458, 2018). "Among the MMPs, MMP9 form a complex with CD44, a cell surface molecule that mediates cell migration and resistance to anti-cancer drugs." (PMID 30157785, 2018). "Together with CD44, endogenous HA is also involved in different stages of malignant tumor progression." (PMID 30375477, 2018). "The finding of a substantial ALDH+CD44+CD24− population stands in contrast to our previous findings in cancer." (PMID 29606612, 2018). "The mtDNA-depleted ESCC cells also had high mRNA and protein expression of cd44, which is considered a cancer stem cell marker in ESCC." (PMID 29447301, 2018). "It is also known that CD44 is highly expressed in cancer stem cells, which are highly resistant to apoptosis and are thought to be essential for metastasis." (PMID 29423071, 2018). "Here, we review current data on the structural and functional properties of CD44, the known roles for CD44 in tumorigencity, the regulation of CD44 expression, and the potential for targeting CD44 for cancer therapy." (PMID 29747682, 2018). "The functional roles of various CD44 isoforms on cancer development and progression remain an active area of investigation." (PMID 29747682, 2018). "In fact, the CD44+ subpopulation of cancer stem cells (CSCs) in solid tumors has been identified as cancer-initiating cells." (PMID 30375477, 2018). "Cells which are known to highly express CD44 and internalise HA are keratinocytes, activated macrophages, fibroblasts, chondrocytes and certain cancer cells." (PMID 29670009, 2018). "CD44 overexpression has been found to be correlated with tumorigenesis and to predict a poor response to anti-cancer therapy." (PMID 30021598, 2018). "Many cancer cell lines expressing CD44 stop proliferation or lose viability by stable knockdown of CD44." (PMID 29674746, 2018).
cancer (continued). "In this review, aberrant splicing events in cancer-associated genes, namely BCL2L1, FAS, HRAS, CD44, Cyclin D1, CASP2, TMPRSS2-ERG, FGFR2, VEGF, AR and KLF6, will be discussed." (PMID 30463359, 2018). "HA has been often modified with a drug carrier to improve drug delivery to CD44-overexpressing cancer cells to effectively suppress cancer growth due to its ability to specifically target CD44." (PMID 30961058, 2018). "mtDNA depletion is a common event in GC, whichmay induce CD44 expression in cancer cells.This depletion has been shown to induce the generationof CSCs, invasion and metastasis, and expression ofepithelial-mesenchymal transition (EMT) markers." (PMID 29845783, 2018). "Overall, cells that highly express CD44 and take up HA, leaving aside cancer cells, are keratinocytes, activated macrophages, fibroblasts and chondrocytes." (PMID 29670009, 2018). "More investigations showed higher level of stem cell (NANOG, OCT4, SOX2) and cancer stem cell (CD44 and ALDH1) markers in BORIS-positive cells in comparition to BORIS-negative cancer cells." (PMID 30323717, 2018). "Other than antibodies, another strategy is to utilize the synthetic peptides that block CD44-HA interactions or to reduce CD44 expression in cancer cells." (PMID 29747682, 2018). "In this study, we investigated the effect of OPN on HCV replication and IFN signaling in cancer stem cells (CSCs) positive for epithelial cell adhesion molecule (EpCAM) and CD44." (PMID 30177680, 2018). "We also attempted to determine cell surface markers that correlate with stem cell signatures, and hypoxia was found to significantly increase the percentage of HMM cells with the high CD44 expression, a putative marker of cancer stemness of HMM." (PMID 30111297, 2018). "CD44 is upregulated in a variety of cancers and can be expressed in its standard isoform, CD44s, or as a number of alternatively spliced variant isoforms, CD44v." (PMID 29747682, 2018). "Several studies in different cancer types link CD44 with activation of signal transducer and activator of transcription 3 (STAT3)." (PMID 29747682, 2018). "CD44 is a cell surface adhesion receptor that is highly expressed in many cancers and has also been identified as a marker for several types of cancer stem cells." (PMID 30165890, 2018). "In the liver xenograft model, although CD44 knockdown attenuated the increase in GS, a key metabolite in differentiating T and P, CD44-silencing in cancer cells improved the accuracy rate of the boundary identification." (PMID 29674746, 2018). "Silencing of CD44 decreased the glucose uptake of cancer cells, ATP production, and lactate production." (PMID 29747682, 2018). "It is demonstrated that high protein expression levels of CSC markers such as ALDH, CD44 and CD133 in tumors is associated with resistance to taxanes in various cancer types." (PMID 30126203, 2018). "Although TNF-α-driven modulation of CD44 expression was already reported in several cancers, this is the first time that a strong link has been found between combined inflammatory cytokines and CD44 expression on HSPCs." (PMID 30116149, 2018). "For all these reasons, CD44 and HA interaction can be exploited as a potential target for cancer therapy." (PMID 30544868, 2018). "Although various factors contribute to cancer stemness and metastasis, and further study is required to understand the function of CD44, we revealed one of the regulatory mechanisms of anoikis resistance." (PMID 29356399, 2018). "CD44 has also been connected to the epithelial-mesenchymal transition (EMT) in cancer cells, which is interesting since EMT has been related to increased migration and invasion of cancer cells." (PMID 30171384, 2018). "The Cancer stem cell phonotype was assessed by the immunohistochemical analysis for the expression of two stem cell markers CD44 and ALDH1." (PMID 29306324, 2018).
cancer (continued). "This study was conducted from 2011 to 2014 to assess the pharmacokinetics, pharmacodynamics, safety, and efficacy of RO5429083 in patients with metastatic and/or locally advanced CD44-expressing malignant solid tumors." (PMID 29747682, 2018). "As an example, osteopontin, which can be secreted by CAFs, is one type of matricellular protein that binds to integrins and the cell-surface proteoglycan CD44 on cancer cells, thus boosting their proliferation, survival, and invasion abilities." (PMID 29883428, 2018). "Human mast cells have been demonstrated to express only the standard form of CD44 under normal conditions, while the CD44 variant 6 and 7 have been identified to interact with OPN in inflammation and cancer." (PMID 29872439, 2018). "Because of the contribution of CD44 to cancer cell function; it is important to understand how CD44 expression is regulated." (PMID 29747682, 2018). "In this work, CD133+/CD44+ cells were approved to have the properties of cancer stem cells as reported." (PMID 30064482, 2018). "Current evidence indicates that CD44s+ cancer cells displaying EMT phenotypes are more intractable than those expressing other CD44 isoforms." (PMID 30042817, 2018). "The effect of HA depends not only on its presentation but also on the cancer cell type and the expression of CD44." (PMID 30375477, 2018). "Recently, CD44, as a receptor for hyaluronan, emerges as mediator of cell-cell and cell-matrix interactions and as pivotal trigger in cancer stem cell communication with their microenvironment." (PMID 30116149, 2018). "As CD44 closely correlates with the oncogenesis and metastasis of various cancers, we then explored the molecular mechanism of CHI3L1/CD44 signaling in GC cells." (PMID 30165890, 2018). "CD44 is a major cell-surface glycoprotein, critical to cancer invasion and metastasis, which can function as a marker for cancer stem cells, cells that can give rise to the many cell types that form tumors." (PMID 30208623, 2018). "Cancer stem cells (CSCs), which have roles in survival andchemoresistance, are commonly analyzed according to theexpression of CD44 and CD24 markers." (PMID 29845783, 2018). "Cancer stem cells also express specific surface markers, including CD44, CD133 and enzyme aldehyde dehydrogenase (ALDH)." (PMID 29760743, 2018). "We also showed a significant association between the stromal CD10 positivity and tumors with cancer stem cell phenotype (expressing CD44 and ALDH1)." (PMID 29306324, 2018). "CD44 plays an indispensable role in activating survival pathways that protect cancer cells from apoptosis." (PMID 29747682, 2018). "Here, we discussed the current understanding of the structure and function role of CD44 in the pathogenesis of cancer." (PMID 29747682, 2018). "In the present study, we found that BIO induced the expression of the cancer stem cell markers EpCAM, CD44, KRT19, and MYC above the levels seen in MeBIO controls without inducing cytotoxicity." (PMID 30177680, 2018). "Targeting overexpressed CD44 in cancer is becoming one of the important strategies in cancer therapy." (PMID 30283149, 2018). "We were recently able to separate cancer cells on the bases of CD44 expression level using flow cytometry." (PMID 29747682, 2018). "A higher sensitivity and selectivity in CD44(+) cancer cells was observed for Apt1-Lip compared to the blank liposomes." (PMID 29747682, 2018). "CD44 is well established cancer stem cell biomarker and expressed in both HCT116 and DLD1 cell lines." (PMID 30250641, 2018). "It was reported that three bona fide markers for cancerous colon stem cells; CD44, Lgr5, and ALDH are highly expressed during the progression to carcinoma and are associated with shorter time to disease recurrence." (PMID 29343849, 2018). "The CD44-positive label between cancer cells was present in multicellular nests, multilayered strands and Indian files." (PMID 28894989, 2017).
cancer (continued). "These evidences implied the possibility of predicting prognosis and making diagnosis at the early stage via molecular imaging of CD44 protein, because CD44 can be expressed in a large amount in cancer cells even at early stage of GC." (PMID 28415792, 2017). "It shows the characteristics of cells undergoing EMT (spindle morphology, reprogramming of epithelial–mesenchymal markers), with acquisition of CSCs markers (CD44+) and is more resistant to chemotherapy than basal-like or luminal cancers." (PMID 28341962, 2017). "One earlier report indicates that the interaction between VCAM-1 and CD44 on a cancer cell's surface can induce ABCG2 expression." (PMID 28969049, 2017). "Due to enhanced invasive properties of CD44+/CD24−/low cancer stem cell population we further tested the migration using xCELLigence® RTCA PD instrument." (PMID 27845900, 2017). "Mouse cancer cells (4T1E/M3) are incubated with biotin-conjugated anti-CD44 antibody for 30 min; then, they are stained with 100-nm streptavidin-conjugated beads." (PMID 28230204, 2017). "In conclusion, a novel cytotoxic drug-loaded nanomedicine platform has been developed, which is based on natural biocompatible biopolymers, capabale of targeting cancer cells with functional surface expression of CD44." (PMID 28212584, 2017). "Recent studies showed that CAFs express high CD44, which is important for maintaining cancer cell stemness." (PMID 28523716, 2017). "In some cancer cell lines, HA activates the major receptor CD44 and promote the expression of NANOG32, OCT-4, and SOX233." (PMID 28484208, 2017). "Our results highlight the possibility that post-surgery fluids contribute to neovascularization, promoting growth and transdifferentiation of cancer stem cells (CD44++/CD117+)." (PMID 29156702, 2017). "Though HA signals through interaction with several cell surface receptors, the best characterized receptors in cancer cells are CD44 and RHAMM (receptor for hyaluronic acid-mediated motility)." (PMID 28460475, 2017). "Now we demonstrated that CD133+/CD44+ cell population from HT-29 or Caco-2 cells exhibited cancer stem cell (CSC) properties with highly expressed Ascl2, which is related to the Hippo signaling pathway." (PMID 29312609, 2017). "Taken together, these data suggested that GDF15 promoted cancer stemness conversion by facilitating CD44+ and ALDH1+ cell formation." (PMID 27903972, 2017). "Cluster of differentiation 44 (CD44), an indicator of cancer stem cells, can be specifically targeted by molecular probes and detected in tissues of GC in a large quantity." (PMID 28415792, 2017). "Two isoforms of CD44 have been reported in many cancers, a commonly expressed CD44s and less commonly expressed CD44v." (PMID 28094783, 2017). "OPN also functions as a ligand for CD44, hyaluronan receptor, which is overexpressed in cancers with poor prognoses." (PMID 29254164, 2017). "Next, we directly observe the binding of nanobeads to cancer cells via anti-CD44 antibodies in a medium condition." (PMID 28230204, 2017). "We also observed a decrease in the mRNA expression of MMP9, a matrix metalloproteinase expressed in CRC31, and a reduction in the mRNA expression of the two established cancer stem cell (CSC) markers CD44 and LGR532,33." (PMID 29167573, 2017). "Functional studies demonstrated that HOXC8 gain of function induces a decrease in the CD44+/CD24-/low cancer stem cell population and proportion of chemoresistant cells, with a concomitant increase in CD24+ differentiated cells." (PMID 28202042, 2017). "Given the role of CD44 in human cancers, we validated our computational modeling results in various experimental settings." (PMID 28279210, 2017). "The HA-SMA-CDF nanomicells were shown to elicit stronger anti-cancer responses against CD44+/CD133+/EpCAM+ CSCs compared with CD44-/CD133-/EpCAM- cells." (PMID 28611316, 2017).